FOXC2-AS1 (FOXC2 antisense RNA 1)
Synonyms: ODRUL
Gene: Long non-coding RNA gene on chromosome 16 (86,564,951 to 86,569,019, reverse strand). Ensembl gene ENSG00000260944.
Diseases named in the same sentence as FOXC2-AS1 in open-access papers:
FOXC2-AS1 is named in the same sentence as 2 diseases in open-access papers, as found by Europe PMC text mining. Sharing a sentence is not in itself a finding about the gene and the disease. The quoted sentences say what the papers report.
cancer (2 papers, 2020 to 2025). A tumor composed of atypical neoplastic, often pleomorphic cells that invade other tissues. "FOXC2 antisense RNA 1 (FOXC2-AS1) was reported, facilitating the proliferation and progression in several cancers." (PMID 32513911, 2020).
FOXC2-AS1 also shares sentences with these, for which no sentence is quoted: osteosarcoma (3 papers).